PDE5A (phosphodiesterase 5A)
Description:
Plays a role in signal transduction by regulating the intracellular concentration of cyclic nucleotides. This phosphodiesterase catalyzes the specific hydrolysis of cGMP to 5'-GMP. Specifically regulates nitric-oxide-generated cGMP.
Synonyms: CGB-PDE; PDE5; CN5A
Tractability: Small molecule: an approved drug acts on it; a structure with a bound ligand is known; a high-quality ligand is known; it has a high-quality binding pocket; it belongs to a druggable protein family. PROTAC: ubiquitination databases record sites on it; a small molecule that binds it is known.
Target class: Enzyme; Phosphodiesterase 5; Phosphodiesterase 5A; Phosphodiesterase
Chemical probes: CHEMBL498486, PD081634, PD084026, PD134684, PD134685, PD134686
Gene: Protein-coding gene on chromosome 4 (119,494,397 to 119,628,804, reverse strand). Ensembl gene ENSG00000138735.
Subcellular location (Human Protein Atlas): Cytosol; Basal body
Pathways (Reactome):
Hemostasis: cGMP effects
Muscle contraction: Smooth Muscle Contraction
Signal Transduction: RHOBTB1 GTPase cycle
Gene Ontology:
Molecular function: 3',5'-cyclic-GMP phosphodiesterase activity; protein binding; 3',5'-cyclic-AMP phosphodiesterase activity; 3',5'-cyclic-nucleotide phosphodiesterase activity; cGMP binding; phosphoric diester hydrolase activity
Biological process: negative regulation of cAMP/PKA signal transduction; cGMP catabolic process; signal transduction
Cellular component: cytosol
Genetic constraint (gnomAD): Loss-of-function variants: 21 observed, 42.93 expected, observed/expected ratio (o/e) 0.49, 90% interval 0.35 to 0.7. The upper end of that interval is the gene's LOEUF score, 0.7, which puts it in group 2 of 6, group 1 being the genes least tolerant of losing a copy. Missense variants: 457 observed, 557.14 expected, observed/expected ratio (o/e) 0.82, 90% interval 0.76 to 0.89. Synonymous variants: 173 observed, 201.97 expected, observed/expected ratio (o/e) 0.86, 90% interval 0.76 to 0.97.
Homologues: Orthologues: chimpanzee PDE5A (99% identical), macaque PDE5A (99% identical), rabbit PDE5A (96% identical), guinea pig PDE5A (95% identical), dog PDE5A (92% identical), pig PDE5A (92% identical), rat Pde5a (92% identical), mouse Pde5a (89% identical), tropical clawed frog pde5a (76% identical), zebrafish pde5ab (72% identical), Drosophila melanogaster Pde11 (45% identical), Drosophila melanogaster Pde8 (14% identical), and 2 more. Paralogues in human: PDE11A (40% identical), PDE6B (28% identical), PDE10A (28% identical), PDE6A (28% identical), PDE6C (28% identical), PDE2A (27% identical), PDE4A (16% identical), PDE8A (16% identical), PDE4C (15% identical), PDE4D (15% identical), PDE8B (15% identical), PDE4B (15% identical), and 8 more.
Diseases named in the same sentence as PDE5A in open-access papers:
PDE5A is named in the same sentence as 301 diseases in open-access papers, as found by Europe PMC text mining. Sharing a sentence is not in itself a finding about the gene and the disease. The quoted sentences say what the papers report.
erectile dysfunction (254 papers, 2005 to 2026). Persistent or recurrent inability to achieve or to maintain an erection during sexual activity. "The individuals carrying a variant of PDE5A polymorphisms (rs12646525 and rs3806808) were associated with a poorer response to Sildenafil treatment in patients with erectile dysfunction." (PMID 37240727, 2023). "The PDE5A affects erectile dysfunction, causing the male sub-fertility." (PMID 34968233, 2019). "Thus, it is possible that genetic markers on NOS1 and PDE5A may help to explain the natural vulnerability to the onset of NO pathway imbalances that culminate in a greater risk of developing erectile dysfunction and having more severe degrees of this disease." (PMID 37240727, 2023). "We compared eight docking suites available with free licenses and attempted to identify drugs for erectile dysfunction using human phosphodiesterase-5 (PDE5A)." (PMID 40491848, 2025). "The first scaffold is represented by tadalafil, a PDE5A inhibitor approved for treatment of erectile dysfunction and benign prostatic hypertrophy that is well known to potently inhibit PDE11A4, albeit at higher concentrations." (PMID 40558524, 2025). "Three erectile dysfunction drugs, sildenafil (Viagra), tadalafil (Cialis) and avanafil (Stendra), which inhibit PDE5a, have gained substantial attention due to their widespread use and potential causal association with skin cancer risk." (PMID 41162377, 2025). "All of these PDE5A inhibitors are used to treat erectile dysfunction, and sildenafil and tadalafil are also used to treat pulmonary arterial hypertension." (PMID 39176072, 2024). "Preventing the degradation of cGMP by PDE5A inhibitors, such as sildenafil and vardenafil, has become a strategy for the treatment of diseases such as pulmonary hypertension and erectile dysfunction." (PMID 36860644, 2023). "Inhibiting the activity of PDE5A has proven to be an effective strategy for treating pulmonary arterial hypertension and erectile dysfunction." (PMID 36860644, 2023). "Recent own experiments demonstrated that Sildenafil, a phosphodiesterase 5A inhibitor drug that has been widely used for the treatment of erectile dysfunction is able to decrease NHE1 phosphorylation, and hence reduce its hyperactivity." (PMID 33693035, 2021). "Among these, PDE-5A is the most widely studied, and its inhibition is a primary mechanism for efficacy of sildenafil in erectile dysfunction." (PMID 15813973, 2005). "In this paper, we compared eight free license docking programs to screen a drug library against the human target, phosphodiesterase 5A (PDE5A), to evaluate their ability to find its known ligand, sildenafil, and other ligands that became erectile dysfunction drugs because they inhibit this target." (PMID 40491848, 2025). "Inhibition of cGMP-specific PDE5A and subsequently elevated cGMP have been used as the therapeutic strategies for improving tissue perfusion via dilation of arterioles in erectile dysfunction, pulmonary hypertension, ischemia/reperfusion injury, myocardial infarction, heart failure, and stroke." (PMID 35822023, 2021). "Additionally, we identified PDE5A, a target for erectile dysfunction drugs, as a potential therapeutic target for CRC, suggesting that such medications may serve as novel treatments by inhibiting PDE5A." (PMID 38762700, 2024). "Two widely used drugs for the treatment of erectile dysfunction, tadalafil and vardenafil, trigger an increase in bone mass in mice through a combination of anabolic and anti-resorptive effects on bone, inhibiting the target enzyme, phosphodiesterase 5A (PDE5A) mechanistically (Kim S.-M." (PMID 34957116, 2021). "PDE5A hydrolyzes cyclic GMP (cGMP) to 5’-GMP, and it is the target of the erectile dysfunction drug sildenafil, which acts as a competitive inhibitor for cGMP degradation." (PMID 40491848, 2025).
pulmonary hypertension (165 papers, 2005 to 2026). Increased pressure within the pulmonary circulation due to lung or heart disorder. "Overexpression of Pde5a may accelerate the formation of pulmonary fibrosis, while down-expression of Pde5a has important roles and effects in pulmonary fibrosis-associated pulmonary hypertension 66,67." (PMID 25278030, 2014). "PDE5a was verified to be the most highly expressed gene in the lung, but not included in the selective gene list, supporting PDE5 inhibitors’ pharmacological effect on pulmonary arterial hypertension." (PMID 39156728, 2024). "PDE5A inhibitors seem to be more effective in reducing right ventricular load in pulmonary hypertension than in HFpEF." (PMID 26924822, 2016). "Thus, pharmacological inhibition of PDE5A activity is in clinical application for treatment of erectile dysfunction and pulmonary arterial hypertension (PAH) using 8 (sildenafil, ViagraTM), 9 (vardenafil, LevitraTM), tadalafil (CialisTM), and avanafil (StendraTM)." (PMID 27213312, 2016).
heart failure (58 papers, 2010 to 2025). Inability of the heart to pump blood at an adequate rate to meet tissue metabolic requirements. "This included up-regulation of genes previously associated with heart failure including genes for the natriuretic peptide A (Nppa), phosphodiesterase 5A (Pde5a), and fibrinogen (Fgb)." (PMID 30038575, 2018). "The second study (doi: 10.1016/j.bbadis.2024.167018) investigated the involvement of OTUD1 in heart failure induced by isoprenaline and myocardial infarction, identifying PDE5A as a critical target." (PMID 39309432, 2024). "PDE5A inhibitors have been used in the clinics with proven effectiveness in improving ventricular function and reducing morality in patients with heart failure." (PMID 33015041, 2020). "We investigated the mechanisms that underpin the beneficial effects of PDE5a inhibition through shRNA on post-MI heart failure." (PMID 26709517, 2015). "Treatment with short hairpin RNA (shRNA) interference therapy targeting phosphodiesterase 5a after myocardial infarction (MI) has been shown to mitigate post-MI heart failure." (PMID 26709517, 2015). "Myocardial PDE5a expression has been shown to increase in patients with advanced heart failure and contribute to LV remodeling subsequent to myocardial infarction." (PMID 26709517, 2015). "Its increased levels have been associated with enhanced proliferation and reduced apoptosis in cardiomyocytes, contributing to protective effects against ischemia-induced heart failure in animal models and mitigating hypertension-induced cardiac hypertrophy by targeting PDE5A." (PMID 41169895, 2025). "In addition, an increased PDE5A expression has been found in different cardiomyopathies that lead to heart failure, such as Chagas, or burn-induced cardiac disease." (PMID 33693035, 2021). "Another indirect evidence for the protective actions of cGMP/PKG system, is that inhibition of PDE5A may be beneficial against heart failure in some clinical setting." (PMID 30249014, 2018). "Our aims in the present study were to confirm the beneficial effects of PDE5a inhibition with Ad-shPDE5a on chronic post-MI heart failure, investigate the role of inflammatory cytokines involved in those effects, and characterize the molecular signaling upstream of the outcomes." (PMID 26709517, 2015). "Taken together, our data additively show that PDE5A alterations begin at a very early stage in cardiac hypertrophy leading to heart failure, and that the reported increase in PDE5 activity occurs before the loss of its intracellular localization to Z-bands and alteration of NOS3 expression." (PMID 21151982, 2010). "In addition, three target genes (ITIH5, NRK, PDE5A) in DCM and RGS4 in heart failure have been reported to be up-regulated, the expression trend of these genes is consistent with our analysis results." (PMID 37268658, 2023). "This further suggests that, in addition to PDE5A, PDE9A may also be a bona fide therapeutic target in heart failure." (PMID 26924822, 2016). "On the other hand, this negative outcome may also be due, in part, to the fact that PDE5A is expressed at low levels in heart failure and myocardial tissues." (PMID 26924822, 2016).
diabetes (47 papers, 2014 to 2025). "There is a relationship between diabetes mellitus and PDE5A polymorphism regarding the response to sildenafil treatment." (PMID 37090981, 2023).
Hypertension (35 papers, 2009 to 2025). The presence of chronic increased pressure in the systemic arterial system. "Inhibition of RNPEP was shown to suppress hypertension in spontaneously hypertensive rats, and inhibition of TNNI3K and PDE5A was shown to be associated with suppressed contractility." (PMID 35172813, 2022). "In a murine hypertension model, oral supplement of a PDE5A inhibitor, sildenafil, prevents and reverses cardiac hypertrophy, which is mediated by an activation of cGMP-dependent protein kinase." (PMID 26091236, 2015). "PDE5A is a hypertension-related gene that regulates cardiac tone and vascular function." (PMID 37090981, 2023).
melanoma (27 papers, 2013 to 2025). A malignant, usually aggressive tumor composed of atypical, neoplastic melanocytes. "When tumor cells are under hypoxic conditions, microphthalmia-associated transcription factors are inhibited, reducing the expression of PDE5A, and promoting the proliferation and metastatic phenotype of melanoma." (PMID 33987019, 2021). "The oncogene BRAF acts through MEK and the cGMP-specific phosphodiesterase PDE5A, which enhances melanoma cell invasion by increasing cGMP and upregulating cytosolic Ca2+, contractility." (PMID 33718200, 2021). "Although there is a lot of evidence indicating melanoma relationship with the use of PDE5A inhibitors such as sildenafil, a recent meta-analysis has pointed to another possibility." (PMID 33718200, 2021). "Animal studies have found that mutations in the BRAF gene result in down regulation of cGMP-specific phosphodiesterase PDE5A, which lead to an increase in colonization of the lungs by melanoma cells." (PMID 28515348, 2017). "They discovered that PDE5A promote melanoma cell invasion through cGMP, Ca2+, and increased contractility." (PMID 28515348, 2017). "Accordingly, immunohistochemistry analysis in a tissue microarray consisting of triplicate cores of 28 primary and 29 metastatic malignant melanoma cases revealed a statistically significant downregulation of PDE5A in metastatic tumors." (PMID 29228762, 2017). "Based on previous research and assumptions about correlations between PDE5A and melanoma, PDE5A—selected from our NGS and bioinformatics analyses—may be considered a crucial factor influencing UTUC tumor cell progression." (PMID 33987019, 2021). "Moreover, oncogenic BRAF induces invasion through downregulation of PDE5A in melanoma cells." (PMID 32764382, 2020). "Although myosin II activity is controlled by BRN2-mediated downregulation of PDE5A and increased calcium signaling in BRAF mutant melanoma, our mechanism seems operative in NRAS mutant melanoma." (PMID 31935375, 2020). "Phosphodiesterase 5A (PDE5A), a member of the cyclic nucleotide phosphodiesterase family, has been shown to play an important role in promoting the progression of thyroid cancer and melanoma." (PMID 38658954, 2024). "We further observed a significant reduction of the expression of PKGI in the highly metastatic BLM melanoma cells, whereas the PDE5A expression was not changed when compared to 1 g control cells." (PMID 32046325, 2020). "Indeed, it was demonstrated that in melanoma cells oncogenic BRAF, through the transcription factor BRN2, was able to suppress PDE5A expression." (PMID 29228762, 2017).
Alzheimer disease (26 papers, 2015 to 2026). A progressive, neurodegenerative disease characterized by loss of function and death of nerve cells in several areas of the brain leading to loss of cognitive function such as memory and language. "In contrast to preclinical and some observational studies, our findings suggest that PDE5A inhibition may be associated with an increased risk of Alzheimer’s disease." (PMID 39951190, 2025). "In our study, genetically predicted PDE5A inhibition was associated with higher MME levels and an increased risk of Alzheimer’s disease." (PMID 39951190, 2025). "As the main active component of ICA metabolite, ICII can suppress Aβ production via promoting the non-amyloidogenic APP cleavage process and markedly decrease the phosphodiesterase-5A (PDE5A) expression to treat Alzheimer’s disease." (PMID 37547333, 2023). "Our data is supported by evidence from a recent proteomic study that showed higher circulating PDE5A levels contributed to a weighted composite score, which predicted incident Alzheimer’s disease and memory deterioration in the Framingham Heart Study Offspring cohort." (PMID 39951190, 2025).
breast carcinoma (25 papers, 2010 to 2025). "Colocalization analysis showed that S100A14 (PP.H4.abf = 0.920) and S100A16 (PP.H4.abf = 0.932) shared causal variation with HER-positive breast cancer, and PDE5A (PP.H4.abf = 0.857) shared causal variation with colorectal cancer (CRC)." (PMID 38762700, 2024). "PDE5A was overexpressed in breast cancer stroma and affected the growth of breast cancer cells by inducing the expression of chemokine CXCL1651." (PMID 38762700, 2024). "PDE5A was overexpressed in various tumors and inhibition of PDE5A can induce apoptosis and attenuate β-catenin-mediated transcription in breast cancer cells." (PMID 33292266, 2020). "Moreover, phosphodiesterase type 5 (PDE5A), described as a mediator of thyroid and breast cancer cell migration, is specifically upregulated in TV1-overexpressing cells and may be responsible for the increased migration." (PMID 33530588, 2021).